INSR (insulin receptor)
Diseases named in the same sentence as INSR in open-access papers (continued):
Sharing a sentence is not in itself a finding about the gene and the disease.
Insulin resistance (continued). "Insulin receptor antagonist S961 was used as an additional model to induce acute insulin resistance in 1.5-year-old male and female mice." (PMID 36640267, 2023). "Previous evidence suggests that homocysteine induces insulin resistance and a diabetic phenotype by acting on the pro-insulin receptor through protein cysteine-homocysteinylation (C-Hcy)." (PMID 38093283, 2023). "ZFYVE28 has great potential to be a therapeutic target to slow insulin receptor degradation and improve insulin resistance." (PMID 37884540, 2023). "By inhibiting the connection between the insulin receptor in the cells and insulin release, the presence of fat that covers the insulin receptor likely contributes to insulin resistance and diabetes mellitus." (PMID 36937314, 2023). "The phenotype–genotype study showed that susceptibility variants in THADA and INSR conferred risk for metabolic syndrome, and variants of DENND1A and TOX3 were associated with insulin resistance in PCOS women." (PMID 36836035, 2023). "Inhibition of tyrosine phosphorylation in substrate 1 of the insulin receptor (IRS-1) caused reduced IR activity, resulting in insulin resistance." (PMID 37507987, 2023). "It has been demonstrated that TNF-α interferes with the insulin receptor signaling pathway and with metabolism of glucose transporters, and, consequently, plays a role in the pathophysiology of insulin resistance." (PMID 38256882, 2023). "The effects of resistin on insulin resistance are not fully understood; however, it appears to influence beta cell apoptosis and insulin receptor expression." (PMID 37761031, 2023). "These factors can impair insulin action and induce insulin resistance by interfering with insulin receptor function or downstream signaling components." (PMID 37680899, 2023). "Implicating a role for InsR dysfunction in rat striatum, InsR substrate 2 phosphorylation at serine residues, an indicator of insulin resistance, is enhanced in the 6-OH-DA model of PD." (PMID 36979453, 2023). "Previous targeted studies have associated insulin resistance with defects in proximal insulin signaling proteins, including AKT, IRS1/2, and the insulin receptor." (PMID 36808134, 2023). "First of all, the insulin receptor dysfunction leading to insulin resistance (IR) is of fundamental importance and defects in the distal insulin signaling pathway (GLUT4 including) are likely drivers of IR." (PMID 36984693, 2023). "In HFD-fed mice, phosphorylated brain insulin receptor (p-IR) protein expression was decreased compared with the control group, suggesting that cerebral insulin resistance is diet-induced." (PMID 36902167, 2023). "Over time, inadequate insulin receptor function and insulin resistance can contribute to the development of various diseases, including diabetes and other metabolic disorders." (PMID 37446104, 2023). "MET is an insulin sensitizer that reduces insulin levels and improves insulin receptor activity, resulting in decreased insulin resistance, lower androgen levels, and improved weight control." (PMID 37002532, 2023). "In particular, low intracellular Mg alters the tyrosine-kinase activity of the insulin receptor, resulting in post-receptor insulin resistance and impairing glucose utilization." (PMID 37940675, 2023). "In the setting of insulin resistance, various metabolic and inflammatory factors inhibit the actions of insulin receptor targets, leading to reduced activation of the PI3K-AKT axis." (PMID 37196634, 2023). "Insulin resistance progression is intimately connected to a defect in insulin receptor (INSR) tyrosine kinase activity." (PMID 37808009, 2023). "PM2.5 exposure also induces insulin resistance through inflammation, disrupting the insulin receptor signaling pathway." (PMID 36851046, 2023).
Insulin resistance (continued). "In this regard, we treated multiparous mice at 3 weeks after the last delivery with S-961, an insulin receptor antagonist that induces insulin resistance and β cell proliferation, and evaluated β cell proliferation in these mice." (PMID 37903900, 2023). "TNF-α is an inflammatory protein synthesised by immune and adipose cells and promotes insulin resistance by alterations in the insulin receptor signaling pathway." (PMID 37215211, 2023). "Genetic insulin receptor deletion induced marked hyperglycemia and insulin resistance in both IRΔPER and IRΔWB mice." (PMID 37100238, 2023). "They affect the structure of cell walls and insulin receptor activity and thus trigger glucose metabolism disorders, generating insulin resistance." (PMID 37111089, 2023). "Two main populations of neurons, POMC and AgRP, express leptin receptor and insulin receptor, and insulin action in these neurons affected systematic insulin resistance." (PMID 36042571, 2023). "In the liver and adipose tissue, IL-6 induces insulin resistance due to insulin receptor inhibition and enhances inflammation." (PMID 37894792, 2023). "It has been suggested that Il-6 and TNF-alpha are involved in the pathogenesis of insulin resistance and type 2 diabetes by inhibiting insulin receptor tyrosine phosphorylation and reducing insulin production in pancreatic beta cells." (PMID 37509592, 2023). "How altered insulin receptor signaling, in the setting of insulin resistance, contributes to the development of mitochondrial dysfunction and thereby precipitates development of heart failure remains to be elucidated." (PMID 37891673, 2023). "Examples are GCK-related hyperglycemia, HNF1Adiabetes, INSR-severe insulin resistance, PPARG-lipodystrophy, mt.3243 A > G syndrome." (PMID 37794142, 2023). "Defects in insulin receptor signaling lead to insulin resistance and diabetes, while certain genetic variations that decrease signaling in these pathways are linked to enhanced longevity, particularly in centenarian populations." (PMID 38203522, 2023). "It is known that low Mg induces insulin-resistance, because it inhibits the tyrosine-kinase activity of the INSR." (PMID 37940675, 2023). "In hepatocytes, PKCε phosphorylates the insulin receptor (IR) in threonine, reducing its ability to auto-phosphorylate into tyrosine and trigger downstream insulin signaling, leading to hepatic insulin resistance." (PMID 37232722, 2023). "The results showed that berberine improved insulin resistance by increasing insulin receptor expression by activating protein kinase C (PKC)." (PMID 36770960, 2023). "In the glycemic context, insulin resistance, driven by mTORC1 hyperactivation-mediated deregulation of the insulin receptor (IR)-PI3K/Akt substrate (IRS) signaling axis, leads to elevated blood glucose levels (hyperglycemia)." (PMID 37894760, 2023). "While insulin resistance can occur distal to the canonical insulin receptor‐PI3k‐Akt signaling pathway, the signaling intermediates involved in the dysfunction are yet to be fully elucidated." (PMID 36807886, 2023). "The inhibition of INSR endocytosis and lysosomal degradation has been confirmed to improve insulin resistance in mice." (PMID 37884540, 2023). "Insulin resistance is induced by interleukin-6 (IL-6), affecting insulin receptor and substrate-1 phosphorylation, common in COVID-19 patients." (PMID 35729170, 2022). "Insulin receptor protein is present in pancreatic β-cells, but the consequences of β-cell insulin resistance are incompletely understood." (PMID 35136059, 2022). "In adipose tissue in obesity, the activation of this pathway results in insulin resistance through IKK-mediated serine phosphorylation of IRS-1 or insulin receptor, leading to the inhibition of insulin-induced serine phosphorylation and downstream signaling." (PMID 36012516, 2022). "Other models of IGF1R or InsR/IGFIR double-knockout in brown adipose tissue also revealed insulin resistance." (PMID 36353242, 2022).
Insulin resistance (continued). "AD patients have shown brain insulin resistance, accompanied by reduced mRNA and protein expression of INSR, insulin receptor substrate (IRS) and IGF-1R." (PMID 36010613, 2022). "SerpinB1 was identified as a hepatokine that promoted pancreatic β-cell proliferation to compensate for insulin resistance in the liver-specific insulin receptor knockout mouse." (PMID 36331940, 2022). "The inhibition of signaling downstream of the insulin receptor is a primary mechanism through which inflammatory signaling leads to insulin resistance." (PMID 36339561, 2022). "Activated MAPK family (p38, ERK, and JNK) can inhibit insulin receptor phosphorylation, and also induce more serious damage to insulin resistance by inducing inflammation." (PMID 36033948, 2022). "As previously shown, the loss of CEACAM1 by >50% lowers hepatic insulin clearance to contribute to chronic hyperinsulinemia and its downregulatory effect on insulin receptor levels to sustain hepatic insulin resistance." (PMID 36009446, 2022). "Recently, Kahn’s lab generated adipocyte-specific tamoxifen inducible insulin receptor deletion (Adipo-ind-IRKO) and demonstrated that 3 days after tamoxifen injection, mice display a massive adipocyte loss and severe insulin resistance." (PMID 35250856, 2022). "In support of this, there is a downregulation of the insulin receptor in the SNpc and an increase in insulin resistance in patients with PD." (PMID 35761385, 2022). "Insulin resistance, which manifests as a reduction of insulin receptor signaling, is known to correlate with pathological changes in peripheral tissues as well as in the brain." (PMID 36009470, 2022). "Several serine/threonine kinases including JNK, mTOR, and p70 S6K cause serine phosphorylation of the insulin receptor substrate (IRS) and have been implicated in insulin resistance." (PMID 35011728, 2022). "The aqueous extract of Syzygium paniculatum fruits alleviated hepatic insulin resistance at a 100 mg/kg dose by reducing the blockage of the insulin signaling pathway via the improvement of insulin receptor (IR and IRS-1) function in HFD-induced diabetic rats." (PMID 35684249, 2022). "Second, the PI3K-Akt signaling pathway is activated by the insulin receptor, which is downregulated in insulin resistance." (PMID 35215222, 2022). "Insulin resistance can be evaluated through the ratio between the serine-phosphorylated insulin receptor substrate with respect to the total phosphorylated insulin receptor substrate, in the brain or peripheral tissues." (PMID 35443732, 2022). "Insulin resistance in cardiomyocytes with impaired Ca2+ homeostasis made us examine expression of insulin receptor (IR) that consists of α and β subunits processed from a common precursor." (PMID 39872684, 2022). "These mice exhibit dramatic insulin resistance with marked hyperinsulinemia due to deletion of the insulin receptor gene in hepatocytes." (PMID 35872305, 2022). "At the molecular level, insulin resistance is a complex pathological condition consisting of serious pathological phenomena, such as suppressed insulin receptor (IR), down-regulated p-AKT, or up-regulated p-s-IRS." (PMID 36699697, 2022). "A possible reason for these findings is that a defective BCAA catabolism regulates rapamycin (mTOR) pathway activation and insulin receptor substrate protein phosphorylation, which lead to insulin resistance and the accumulation of cytotoxic metabolites." (PMID 36014850, 2022). "BCAA-mediated insulin resistance occurs because it inhibits the phosphorylation of the insulin receptor (IRS-1)." (PMID 36542005, 2022). "Secondly, free fatty acid secretion from the visceral adipose tissue can inhibit insulin receptor expression, thereby contributing to the incidence of insulin resistance." (PMID 35145487, 2022). "In insulin resistance insulin receptor signaling is perturbed, GLUT4 translocation is attenuated and circulating glucose cannot be taken up." (PMID 35615361, 2022).
Insulin resistance (continued). "The authors find that the insulin receptor forms dynamic clusters during insulin signaling and that these clusters become dysfunctional in insulin resistance." (PMID 36473871, 2022). "For example, IL-6 directly inhibits insulin sensitivity and upregulates the release of hormones that contribute to insulin resistance via induction by insulin receptor's signal transduction in hepatocytes." (PMID 35647197, 2022). "IRS-1 and IRS-2 are downstream signal factors of InsR, and those are the critical kinase of glucose uptake and the target of insulin resistance." (PMID 35845787, 2022). "On the other hand, reduced insulin clearance in the liver can cause chronic hyperinsulinemia, followed by downregulation of insulin receptor and insulin resistance." (PMID 36009446, 2022). "GM3 regulates EGFR and InsR signaling through lateral interactions with these receptors, and development of insulin resistance involves increased GM3 expression during obesity-induced inflammation." (PMID 35628171, 2022). "Previous reports have shown that PPARβ agonists, such as GW501516, ameliorates insulin resistance by increasing the expression of the insulin receptor, of significance for treatment of insulin resistance in patients with type 2 diabetes mellitus." (PMID 35769384, 2022). "Cloning of the insulin receptor and unraveling of the intracellular signaling systems primed by insulin opened a new era in the understanding of mechanisms of insulin resistance." (PMID 36289636, 2022). "Insulin resistance can be induced in astrocytes through the fructose induced insulin resistance cell model resulting in decreased insulin receptor and Akt phosphorylation." (PMID 36038539, 2022). "It was observed that the phosphorylation of the insulin receptor was inhibited, indicating that CK improved insulin resistance through autophagy." (PMID 35745765, 2022). "Impaired insulin responsiveness/insulin resistance is commonly linked to serine phosphorylation of IRS-1; phosphorylation of IRS-1 on Ser307 (human Ser312) results in its dissociation from the insulin receptor, and also impairs insulin downstream signaling." (PMID 35739993, 2022). "In line with the effects of sEH gene knockout, administration of EET analogues reduced hepatic fibrosis, insulin resistance, and inflammation induced by HFD, which is associated with an increase in HO-1-PGC1α and enhanced insulin receptor phosphorylation." (PMID 35744996, 2022). "This suggests that bilberry prevents the development of insulin resistance in the liver by increasing insulin receptor expression." (PMID 36232316, 2022). "MMP‐8 brings about human insulin receptor protein cleavage which in turn results in insulin resistance and consequently, diabetes mellitus." (PMID 35818743, 2022). "Increasing evidence suggests that alterations in the insulin receptor trafficking can lead to severe insulin resistance." (PMID 35808897, 2022). "Insulin resistance is defined as insulin receptor damage and the disruption of insulin action, where insulin unable to take up the glucose into the cell, resulting in a hyperglycemia." (PMID 35487948, 2022). "Visceral adipose tissue-specific downregulation of the insulin receptor was found to be an early event in obesity-related adipose cell dysfunction, which increases systemic insulin resistance in obese humans." (PMID 35721732, 2022). "Polysaccharides can also enhances insulin receptor sensitivity leading to reduced insulin resistance, can elevate glycogen synthesis in the liver and can improves the rate of glucose utilization and anti-inflammatory activity in peripheral tissues." (PMID 35600869, 2022). "DM1 patients show insulin resistance due to the aberrant splicing of the insulin receptor (IR) mRNA, which is highly expressed in skeletal muscle." (PMID 35270043, 2022).
Insulin resistance (continued). "The cleavage of Insulin Receptor by MT1-MMP also contributes to obesity-induced insulin resistance and inhibition of MT1-MMP activities normalizes metabolic dysfunctions in diabetic mouse models." (PMID 35768470, 2022). "At the molecular level, abnormalities in the phosphorylation of the insulin receptor, or insulin-receptor substrate, have been suggested to be the most prominent among the mechanisms of insulin resistance in PCOS." (PMID 36611967, 2022). "TNF-α and IL-6, as proinflammatory factors, from obese adipose tissue contribute to insulin resistance by impairing insulin receptor activation, upregulating insulin and insulin-like growth factor-1 (IGF-1) levels." (PMID 35964108, 2022). "Insulin resistance is characterized by the impairment of the insulin receptor substrate/phosphatidylinositol 3-kinase/protein kinase B (Akt) pathway." (PMID 35563793, 2022). "Proia’s group reported that these mice display enhanced phosphorylation of InsR in skeletal muscle following insulin injection, enhanced glucose and insulin tolerance, and reduced susceptibility to high-fat diet (HFD)-induced insulin resistance." (PMID 35628171, 2022). "Aβ can competitively bind to insulin receptors and stimulate insulin resistance, and Aβ has been shown to inhibit autophosphorylation of the insulin receptor and reduce insulin receptor levels and activity." (PMID 36117918, 2022). "Insulin resistance occurs when normal concentrations of insulin fail to achieve an appropriate biological response downstream of the insulin receptor." (PMID 36465627, 2022). "The potential effect of IGF1R antibodies on INSR signaling is of special concern given that these antibodies can alter INSR function, leading to insulin resistance and adverse effects on glucose and carbohydrate metabolism." (PMID 36479090, 2022). "Hyperinsulinemia impairs insulin receptor function, which overtime leads to insulin resistance and T2D." (PMID 35785485, 2022). "Our results suggest the participation of Sam68 in insulin receptor signaling, mediating, possibly, the insulin effect in GCs and pointing to a new target in insulin resistance observed in GCs from PCOS women." (PMID 36139396, 2022). "In our previous studies, we have reported that SIT controls insulin resistance and hyperglycemia by activating insulin receptor (IR) and glucose transporter 4 (GLUT 4) proteins in adipose tissues of type-2 diabetic rats." (PMID 33917607, 2021). "Ronald Kahn, David Neville, and Jesse Roth carried out the first receptor-binding assays and concluded that the levels of the insulin receptor are reduced in obese animals, providing a plausible explanation for insulin resistance." (PMID 34717951, 2021). "E3 ubiquitin ligases play pivotal roles in the process of insulin resistance and directly degrades the insulin receptor, insulin receptor substrate, and other key insulin signaling molecules via the ubiquitin-proteasome system (UPS)." (PMID 34603025, 2021). "After ubiquitination of the insulin receptor, it can be further degraded by the proteasome, and the level of the insulin receptor on the cell membrane surface is reduced, resulting in insulin resistance." (PMID 34603025, 2021). "TNF-α, one of the most commonly studied cytokines in relation to insulin resistance, has been shown to inhibit insulin receptor signaling." (PMID 34078385, 2021). "These cytokines can interfere with insulin receptor signaling pathways, which in turn induce local (fat) and systemic (liver and skeletal muscle) insulin resistance." (PMID 34863096, 2021). "In humans, insulin resistance and obesity are associated to an increased PTP activity towards the insulin receptor and increased expression of LAR in the subcutaneous adipose tissue." (PMID 34071721, 2021).